CD274 (CD274 molecule)
Diseases named in the same sentence as CD274 in open-access papers (continued):
Sharing a sentence is not in itself a finding about the gene and the disease.
tumor (continued). "The expression of CD274 and CCR6 was also evaluated on non-hematopoietic cells present in both non-tumor and tumor samples, as well as in tumor samples with non-desmoplastic or desmoplastic growth patterns." (PMID 37370832, 2023). "Our research mainly assessed the heterogeneity of tumor-infiltrating immune cells in OV TME and found that three immune checkpoint genes CD274, CTLA-4, and PDCD1LG2, showed negative correlations with risk scores." (PMID 35137909, 2022). "Referring to the TCGA HNSC tumor dataset, we found a positive correlation between IFN-γ-related genes (IFN-γ, CD8A, and STAT1) and PD-L1 (CD274), but not between EGF-related genes (EGFR, AKT1, and MAP2K7), which seems to support the results of this study." (PMID 35456895, 2022). "A large analysis of 118 187 tumor samples showed that CD274 amplification was identified in 0.7% of the samples and did not correlate with PD‐L1 expression." (PMID 33314633, 2021). "For instance, the immunosuppressive factors CD274 and IL8 identified from the cell lines were also validated by UALCAN and Kaplan–Meier Plotter, which contained data from tumor tissue rather than the cell lines." (PMID 31293831, 2019). "PD-1 has two ligands, PD-L1 (B7-H1, CD274) and PD-L2 (B7-DC, CD273), which are mainly expressed on non-hematopoietic cells, including tumor cells in numerous cancers." (PMID 29868474, 2018). "In line with this and unlike reported for basal squamous tumors in the TCGA publication, CDKN2Ahigh tumours also do not show an elevation of PDCD1, CD274 and CTLA4 expression." (PMID 30258198, 2018). "In our patient, EBER in situ hybridization revealed absence of EBV in the tumor cells, and it is unlikely that the efficacy of anti-PD-1 therapy is affected by EBV-related CD274 and PDCD1LG2 amplification." (PMID 27012666, 2016). "Interestingly, despite their central roles in anti-tumor immunity, our in silico analyses did not reveal significant correlations between the expression of PSD3, CD274, or TNFSF18 and the infiltration of CD8+T cells or natural killer (NK) cells." (PMID 40895529, 2025). "Healthy adult bone marrow Erythroid cells also differ from the tumor-induced Erythroid cells, as they do not express any PDCD1 (PD-1) or CD274 (PD-L1) genes, which suggests restricted immunosuppression by healthy adult bone marrow Erythroid cells compared with the tumor-induced ones." (PMID 39038020, 2024). "Unlike other anti-CD274 mAbs which are designed to eliminate any ADCC/CDC activity as a precaution of off-tumor cytotoxicity, the IgG1-Fc region of avelumab binds to FcγRs on NK cells and directly mediates cellular cytotoxicity against tumor cells." (PMID 37215135, 2023). "However, the increased expression of tumor cell PD-L1 in S/R RCC tumors and the responsiveness of these tumors to PD-1 inhibitor monotherapy appeared to be independent of CD274 gene amplification." (PMID 33547292, 2021). "Moreover, a negative correlation between CD274 (PD-L1) and USP12 transcript levels were found in NSCLC tumours." (PMID 34381028, 2021). "Meanwhile, our results indicated that there was no obvious tumor cells in the anti-CD47 and anti-CD274 group, suggesting that synergy CD47 antibody and CD274 antibody could effectively prevent CTCs from forming metastases in the lungs." (PMID 30872703, 2019). "Deletions of PD-L1 (CD274) and PD-L2 (PDCD1LG2) genes were always accompanied by JAK2 deletion, suggesting that JAK2 deletion may be a mechanism to safeguard tumor cells from activated cytotoxic T cells in the absence of negative regulators PD-L1/PD-L2." (PMID 28977839, 2017). "This analysis showed an overall decrease in the percentage of monocyte subpopulations expressing CD206 or CD274, as well as in the expression of these markers (MFI) in the blood samples, either from CRCLM or control (CTR), when compared to the tissue samples (non-tumor or tumor) from CRCLM patients." (PMID 37370832, 2023).
tumor (continued). "Additionally, our results also showed that tumor samples with a desmoplastic growth pattern have a lower expression of CD206 and CD274 compared to tumor samples with non-desmoplastic tumor growth, being significantly different for CD274 expression on non-classical monocytes." (PMID 37370832, 2023).
cancer (13,781 papers, 2008 to 2026). A tumor composed of atypical neoplastic, often pleomorphic cells that invade other tissues. "CD274 (encoding PD-L1) was expressed diffusely in subpopulations of cancers, and its abundance was weaker than that of VSIG4." (PMID 39920772, 2025). "CD274, encoding PD-L1, plays a critical role in cancer by suppressing immune responses through interaction with PD-1 on T cells." (PMID 39401197, 2024). "Activation of this pathway also culminates in a dampened anti-cancer immune response by increasing the binding of XBP1s to the CD274 promoter, encoding for PD-L1." (PMID 38383727, 2024). "A comprehensive analysis of 33 different cancer types was performed to further study the association between PD-L1 (also known as CD274) and prognosis." (PMID 38166842, 2024). "Programmed Death Ligand -1 (CD-274) is one of the immune checkpoint ligands that do not only cause the immune escape of cancer cells, but also have some intracellular effects in these cells." (PMID 37193972, 2023). "PD-L1 (B7-H1), encoded by CD274, tended to be overexpressed and was considered a definitive biomarker for several cancers treated with anti-PD-1/PD-L1 antibodies." (PMID 36983639, 2023). "We analyzed infectivity, replication, cytotoxicity, CD107α upregulation of CD8+ and CD4+ T cells, CD274 (PD-L1) blockade of cancer cells by virus-encoded anti-PD-L1 scFv, and the release of growth factors and cytokines." (PMID 37762490, 2023). "This study proves that rare structural variants in CD274 UTR region exist in various cancer in Chinese population for the first time, which can induce immune escape and be used for prediction of response to ICIs." (PMID 36717553, 2023). "PD-L1, also known as CD274 or B7 homolog 1(B7-H1), is a transmembrane protein expressed on cancer cells that causes immunosuppression by binding to PD-1 in T cells." (PMID 37302081, 2023). "PD‐L1 (encoded by CD274) is frequently overexpressed in various human cancer and expressed in 19.6%–65.3% of NSCLC reportedly." (PMID 35083874, 2022). "PD-L1 is a type 1 transmembrane protein that is encoded by the CD274 gene in humans and is overexpressed in some kinds of cancers." (PMID 35971127, 2022). "Specifically, except for immune cell infiltration, it is significantly positively correlated with immune checkpoint genes, especially CD274 (PD-L1), and cancer-associated fibroblasts." (PMID 36212130, 2022). "Programmed death protein 1 (PD-1, encoded by the PDCD1 gene) and its ligand programmed death-ligand 1 (PD-L1, encoded by the CD274 gene) function in the immunotherapy of cancer by evading T cell immunity." (PMID 36499447, 2022). "CD274 encodes PD-L1, which is well known for its suppressive role in blocking T-cell activation and has therefore already been used as a target in cancer immunotherapy." (PMID 36675674, 2022). "CD274, the gene encoding PD-L1, is commonly used in immunotherapy and presents effectiveness against many cancer types." (PMID 35401877, 2022). "Fifteen gene signatures were enriched in the higher CD274 expression group, and several enriched pathways are cancer-associated immune responses." (PMID 36362062, 2022). "Especially, high expression of LAG3, CTLA4, PDCD1 (PD-1), IDO1, and CD274 (PD-L1) were widely reported to be associated with suppressive immune response and suppressed T cell function in cancer." (PMID 35902970, 2022). "By analysis of CD274, the association between the biomarker and response was reversed in several cancer types." (PMID 35669882, 2022). "By utilizing integrative analysis, SPHK1 has been associated with immune features across multiple cancer types and positively correlated with programmed cell death ligand 1 (PD-L1, also known as B7-H1/B7 Homolog1 or CD274)." (PMID 36050478, 2022). "Previous studies have not clarified the difference between sporadic MSI and Lynch syndrome-associated cancers in terms of the expression of CD274." (PMID 36013315, 2022).
cancer (continued). "CD274 and CD8A can reflect PD-L1 and PD-1 expression values, suggesting that Ms are associated with novel immunotherapy for some cancers." (PMID 35265626, 2022). "METTL1 expression was positively correlated with PVRL2 in nearly all cancers, whereas, it was negatively associated with KDR and CD274 in nearly all cancers." (PMID 35432338, 2022). "In contrast, various genetic alterations in the CD274 gene were reported somatically in cancer tissue, with gene mutation, alteration, and loss being the most prevalent occurrences, and skin cancer being the most affected cancer type." (PMID 35955729, 2022). "PD-L1, also identified as B7-H1 encoded by the CD274 gene, is a co-inhibitory molecule expressed on activated immune cells, by which cancer cells utilised to evade the host’s immune response." (PMID 36009373, 2022). "The results suggested that UBE2C expression was positively associated with the immune checkpoint-related genes in 31 cancers, which mainly included CD274, CTLA4, HAVCR2, LAG3, PDCD1, PDCD1LG2, SIGLEC15, and TIGIT." (PMID 34858987, 2021). "A significant positive correlation was observed between gene expression of CD274 (PD-L1) and CDKN2A/MTAP in a subset of TCGA cancers, which indicates decreased PD-L1 expression in cancers with 9p21 loss." (PMID 34556668, 2021). "Programmed death-ligand 1 (PD-L1) is a type 1 transmembrane protein encoded by the human CD274 gene that is overexpressed in some types of cancer, and PD-1 is an inhibitory receptor encoded by the PDCD1 gene that is located on the surface of all T cells." (PMID 35126059, 2021). "Therapy responses are not limited to those cancers in which CD274 expression is detected but high CD274 is associated with a greater response." (PMID 34067485, 2021). "The CD274 gene, which plays an important role in the immune escape of cancer cells, encodes programmed death ligand-1 (PD-L1) expressing in many cancer cells and immune cells." (PMID 34306024, 2021). "Programmed cell death-ligand 1 (PD-L1), encoded by the CD274 gene, is the ligand of programmed cell death-1 (PD-1) and exists in several cancers, and it has the ability to inhibit T cell activation." (PMID 34307695, 2021). "The importance of this regulatory region is also illustrated in frequent CD274 3’ UTR structural variants found in many cancers, causing elevated surface PD-L1 expression in cancer cells." (PMID 31729316, 2019). "(G) Box plot of CD274 variant 1 and CD274-L2A expression (in TPMs) in the indicated cancer patient (n = 24 for each indication) and healthy control samples (n between 2 and 156)." (PMID 31729316, 2019). "Consistent with two recent reports, variant CD274-L2A was readily detected in a variety of healthy tissues and cancer samples." (PMID 31729316, 2019). "The gene signature associated with this phenotype, additionally including immune regulatory genes IDO1, FOXP3, PDCD1, CTLA4, and CD274/PD-L1, has been associated with an improved prognosis in multiple cancer types." (PMID 29064420, 2017). "Additionally, M2d cells highly expressed Cd274 (which encodes programmed death–ligand 1 [PD-L1]), but Cd274 expression was reduced when Yap1 was silenced in cancer cells." (PMID 39946200, 2025). "Moreover, YAP/TAZ activation in human cancer cells directly upregulated the expression of immune checkpoint PD-L1 (CD274, B7-H1) to inhibit T cell function and cause immune evasion." (PMID 40940864, 2025). "Additionally, 22 of 32 cancers showed a significant correlation between the risk score and CD274 expression." (PMID 40565338, 2025). "To expand the understanding of the role of TUBA1C across a wide range of cancers and tissues, we conducted a comprehensive analysis focusing on its association with CD274, variations in gene expression, CNV, and methylation discrepancies, in addition to their implications for prognosis." (PMID 39301023, 2024).
cancer (continued). "However, the expression of CD274 (PD-L1), myeloid-derived suppressor cells (MDSCs), and cancer-associated fibroblasts (CAFs) showed significant differences between the two groups." (PMID 36902678, 2023). "Additionally, the low-risk group presented with higher T cell dysfunction, CD274, Merck18, and cancer-associated fibroblast levels, and lower myeloid-derived suppressor cells level." (PMID 37327286, 2023). "An interesting genetic mechanism for enhanced immune suppression was discovered, whereby 3’UTR loss in PD-L1 (CD274) resulted in enhanced expression and more effective immune evasion in multiple cancers, though the precise mechanism for this upregulation was unclear at the time." (PMID 36864508, 2023). "Interestingly, NF-κB regulates the level of CD274 (encoding PD-L1) in various cancer types, and p65 enhances the transcriptional activity of NF-κB and p65 facilitates the expression of PD-L1 through binding to PD-L1 promoter." (PMID 37871286, 2023). "Indeed, loss of IRF1 expression in vitro in cancer cell lines results in a significant reduction of CD274 expression." (PMID 37190121, 2023). "Finally, we obtained CD274 gene expression and glycolysis scores of patient samples from TCGA across various cancer types to identify any association of metabolic reprogramming and/or immune-suppressive aspects with patient survival." (PMID 36354714, 2022). "Furthermore, the findings revealed that IDI2-AS1 had a stable association with the expression of PD1 (PDCD1) and PD-L1 (CD274) to serve as a potential prognostic marker or therapeutic targets of cancers integrated with m6A-related regulators." (PMID 33746977, 2021). "In various cancer types, programmed cell death-ligand 1 (PD-L1; encoded by the CD274 gene) and programmed cell death 1 ligand 2 (PD-L2, CD273, encoded by the PDCD1LG2) suppressed T cell activation and facilitated immune evasion by binding to PD-1 on lymphocytes." (PMID 34796785, 2021). "More importantly, the CD274/PDCD1LG2 expression was associated with the cancer immunity." (PMID 33833994, 2021). "Consequently, it is of great significance to comprehensively investigate the association of the CD274/PDCD1LG2 expression with TMB levels among the patients with cancer, using the TCGA-derived high-quality matched data." (PMID 33833994, 2021). "PD-L1, encoded by the gene CD274, interacts with the corresponding receptor programmed cell death protein 1 (PD-1) on the surface of immune cells, which inhibits the antitumor activity of immune cells and allows cancer cells to escape immune surveillance." (PMID 32967712, 2020). "Immune checkpoint therapy, such as the reactivation of T-cell activity by targeting programmed cell death 1 (PD-1) and its ligand PD-L1 (also called B7-H1 and CD274) has been found pivotal in changing the historically dim prognoses of malignant tumors by causing durable objective responses." (PMID 32377193, 2020). "Currently inhibitors of the immune checkpoints CTLA-4 (cytotoxic T-lymphocyte-associated protein 4) and CD274 (Programmed death-ligand 1, PD-L1 or B7H1) have been approved for the treatment of several cancer types, further underlining the importance of this pathway." (PMID 27683114, 2016). "In all, these pan-cancer observations offer insights on the classification of patient samples with more vs. less PD-L1 (or CD274) and glycolysis, as well as the worse probability of patient survival linked with their parallel enrichment, which is largely uniform across all evaluated cancer types." (PMID 36354714, 2022). "Indeed, p300 is implicated in promoting the expression of CD274 encoding programmed death-ligand 1 (PD-L1), which may confer resistance to cancer immunotherapy in PCa." (PMID 34201346, 2021). "PD-L1 (gene: CD274) is also elevated in patients with HNSCC, and its expression is associated with cancer chemoresistance." (PMID 41385756, 2026).
cancer (continued). "CD274 plays a complex role in inflammation by acting as a negative regulator of immune responses to minimize tissue damage, but cancer cells also use it to evade immune attack." (PMID 41465460, 2025). "To test this possibility in a broader oncogenic context, we analyzed the correlation between MSL1, MSL3, and CD274 expression across multiple cancer types using the TIMER2.0 database." (PMID 41409271, 2025). "In this manner, even within the same cancer tissue, expression of CD274 and hot/cold markers exhibited clear localization biases." (PMID 40670667, 2025). "The PD-L1 (also known as CD274 or B7H1) immune checkpoint has been extensively studied in HNSCC because it plays a critical role in cancer evading immune recognition." (PMID 40278305, 2025). "Human cancer data also revealed diurnal variations in PD-1 and PD-L1 (CD274) expression, peaking during the resting phase." (PMID 40075745, 2025). "The regulation of CD274 (PD-L1), a pivotal immune checkpoint in cancer immunotherapy, remain incompletely understood." (PMID 41409271, 2025). "Immunotherapy analysis showed that the levels of myeloid-derived suppressor cells (MDSC), cancer-associated fibroblasts (CAF), CD274 (PD-L1), and immune exclusion were lower in the high-ratio group compared to the low-ratio MSMB/Epithelial_cells group." (PMID 40002900, 2025). "In solid tumor investigations, AMPK blocked β-catenin trans-activation via activation-dependently inhibiting AKT-mediated phosphorylation of the β-catenin S552 site, which in turn reduced the transcript levels of CD274 (PD-L1) in cancer cells." (PMID 41451233, 2025). "Cd274 expression in M2d cells and Pdcd1 expression in T cells were decreased when cancer Yap1 was silenced." (PMID 39946200, 2025). "In other cancers, oncogenic Ras promotes immunosuppression by stabilizing CD274 mRNA, which encodes PD-L1." (PMID 40723291, 2025). "CD279 (PD-1) and CD274 (PD-L1) are central immune checkpoint molecules targeted in cancer immunotherapy." (PMID 41409271, 2025). "The finding that CD274 is involved in eight RCD processes (apoptosis, autophagy, cuproptosis, efferocytosis, ferroptosis, necroptosis, pyroptosis, and necrosis) expands our understanding of the multifaceted roles of PD-L1 in cancer biology." (PMID 41048343, 2025). "PD-L1, encoded by CD274, is a ‘don’t kill me’ signal that dampens anticancer T cell responses and is a major target for cancer immunotherapy." (PMID 40355593, 2025). "Collectively, these findings demonstrate that MSL1 acts as a positive regulator of CD274 expression across diverse cancer cell lines, as evidenced by reciprocal and consistent results from both gain- and loss-of-function experiments." (PMID 41409271, 2025). "Programmed death ligand 1 (PD-L1, officially known as CD274) is an immune checkpoint molecule that suppresses the immune response, and anti-PD-L1 antibodies are a mainstay of modern cancer treatment." (PMID 40704506, 2025). "MSL1 expression correlates with immune infiltration across cancers, and its deletion markedly reduces CD274 expression." (PMID 41409271, 2025). "In the context of cancer, there is a mechanism leading to the induction of CD274 transcription that can be considered specific to the stressful environment characteristic of tumors, namely hypoxia." (PMID 41425548, 2025). "CD274 (PD-L1), a key immune checkpoint and classic target for immunotherapy, bound to PD-1 on T-cells, leading to their exhaustion in multiple cancer types." (PMID 40529377, 2025). "The immunoglobulin-associated receptor family (TIGIT, CTLA4, CD274, and BTLA) have inhibitory effects on T cell function and have been used as a part of immunomodulatory strategy for treating cancers." (PMID 40173324, 2025). "Programmed death ligand-1 (PD-L1, encoded by CD274 gene) is highly expressed in a variety of human cancers." (PMID 39901136, 2025). "In particular, CD274 is already the basis of FDA-approved immune checkpoint inhibitors in various cancers." (PMID 40895529, 2025).